INS (insulin)
Diseases named in the same sentence as INS in open-access papers (continued):
Sharing a sentence is not in itself a finding about the gene and the disease.
diabetes (continued). "We could only explain one-third of the variance in HbA1c by glycemic factors, age, sex, BMI, and ethnicity among individuals without diabetes, whereas these factors explained nearly 80% of the variance in HbA1c among non-insulin-treated T2D patients with HbA1c concentrations ≥6.5%." (PMID 29855488, 2018). "Similarly, FF and OS were not affected by diabetes or insulin use." (PMID 29423104, 2018). "In the setting of heart transplantation, one retrospective study demonstrated that intravenous (IV) and subcutaneous (SQ) insulin protocols with a glucose target of 80–110 mg/dL [4.5–6.1 mM] could safely be implemented in both patients with and without pretransplant diabetes." (PMID 29623219, 2018). "Another involved Fabrice Bonnet, a diabetes researcher at the Institute for European Expertise in Physiology (IEEP), who led a study between 2012 and 2014 to determine whether daily consumption of sweeteners included in carbonated soft drinks affected insulin sensitivity." (PMID 29560842, 2018). "Thus, the use of protein to increase postprandial insulin may be contraindicated in people with and without diabetes." (PMID 30126094, 2018). "Furthermore, brain tissue from AD patients without diabetes show insulin signaling impairments." (PMID 29743868, 2018). "Indeed, in some cases of adult-onset type 1 diabetes, the slow progression to beta-cell failure may not require insulin treatment immediately; thus, the lack of a need for insulin is not particularly discriminatory for monogenic diabetes." (PMID 30377832, 2018). "The dietary intervention elicited marked increases in meal-stimulated insulin secretion and beta-cell glucose sensitivity, along with decreased fasting insulin resistance and decreased fasting and postprandial plasma glucose concentrations, in individuals with no history of diabetes." (PMID 29425120, 2018). "Furthermore, a potential role of IDE in the development of diabetes and Alzheimer’s disease might be addressed using insulin or amyloid-β peptide, respectively, that is not degraded by IDE but has a normal susceptibility to other degradation pathways." (PMID 30545091, 2018). "In this respect, the effect of HX-1171 on lowering the high blood glucose levels and improving insulin secretion in STZ-induced diabetic model is very promising, and our results suggest that HX-1171 may be applied and developed as a therapeutic agent for diabetes-related diseases." (PMID 29849938, 2018). "It is possible to achieve a reduction in postprandial glycemia and insulin without a deleterious effect on beta-cell glucose sensitivity by substituting part of dietary carbohydrate with iso-caloric protein and fat in subjects without type 2 diabetes mellitus (T2DM)." (PMID 30213037, 2018). "In the present study, the relation between self-reported insulin use and diabetes burden was independent of worries about hypoglycemia and self-reported occurrence of severe and non-severe hypoglycemic events in the previous year, suggesting other aspects of insulin treatment might play a role." (PMID 29347915, 2018). "Finally, the studied patient population represents those from endocrinology clinics within four large tertiary hospitals in China, and thus may not be representative of the entire insulin-prescribed diabetes population in China." (PMID 29699587, 2018). "The only statements from the Growth Hormone Research Society are that “fasting insulin levels are not routinely measured” and “caution should be exercised when considering the decision of continuing GHT in conditions where there is a known risk of diabetes in the transition age”." (PMID 29942285, 2018). "Hence, to address possible residual confounding, we also assessed MD differences by duration of insulin treatment and insulin glargine use in case-only analyses, and we performed additional analyses using non-insulin-treated diabetes patients as an active comparator." (PMID 30092829, 2018).
diabetes (continued). "Furthermore, researchers have shown that in patients with poorly controlled diabetes, the lack of postprandial ghrelin decreases results from a profound insulin inefficiency and may explain polyphagia." (PMID 30011905, 2018). "Diabetes Mellitus (DM) is a metabolic disorder characterized mainly by chronic hyperglycemia in which pancreas beta-cells produces little or no insulin (type 1 DM); or insulin resistance (DM type 2)." (PMID 30405072, 2018). "Furthermore, we had no information regarding diabetes medications, and whether patients were taking oral agents or insulin." (PMID 29668755, 2018). "Early diabetes is generally regarded as the phase that optimizes the chances of inducing remission, although experience with bariatric surgery has shown that large improvements in glycemic control can be achieved even in non-obese patients with long-standing, insulin-treated type 2 diabetes." (PMID 30142908, 2018). "It was noticed that other diabetes and hypertension medicines commonly used in the private sector and mentioned in the state Standard Treatment Guidelines, such as enalapril, losartan, atorvastatin, pioglitazone, glimepiride and insulin were not procured by PHCs in the study talukas." (PMID 29527334, 2017). "Gestational diabetes mellitus (GDM) is defined as “any degree of glucose intolerance with onset or first recognition during pregnancy that is not clearly overt diabetes” regardless of whether insulin is used for treatment or whether the condition persists after pregnancy." (PMID 28644881, 2017). "Devices for the delivery of insulin may mimic how insulin is secreted and could potentially reduce diabetes-related complications, but they do not address the underlying autoimmune pathology, nor is insulin release fully coupled to second-to-second fluctuating glucose levels." (PMID 29075262, 2017). "However, it has been established that the strict control of glucose levels, especially in patients with a recent diagnosis of diabetes, and the maintenance of higher levels of C-peptide secretion result in a lower frequency of microvascular complications regardless of the insulin regimen." (PMID 29218029, 2017). "Consequently, glucose fails to stimulate insulin secretion, leading to the development of diabetes." (PMID 29087246, 2017). "It seems that, after differentiation, insulin-producing cells do not have a very long lifespan in vivo, and thus we may need to give more than one infusion of these cells to completely ameliorate diabetes in NOD mice." (PMID 28701182, 2017). "In addition, insulin sensitizers (such as metformin, rosiglitazone and pioglitazone) used when appropriate and in patients with mild-to-moderate CKD (within CKD stage 3a, estimated glomerular filtration rate > 45 mL/min/1.73 m2), can be administered in conjunction with other diabetes treatment." (PMID 28264439, 2017). "So far, none of the home-based studies of closed-loop insulin delivery have focused specifically on patients with HbA1c below 7·5% who might be early adopters of closed-loop technologies striving to further improve control of their diabetes." (PMID 28094136, 2017). "This could not be explained by the type of diabetes medication (oral or insulin), as the percentage of those using oral medication/insulin did not substantially differ between the Dutch and the other ethnic groups (94% using oral and 23% using insulin)." (PMID 28154830, 2017). "Understanding the interaction between insulin signaling molecules and key regulatory proteins that are involved in spatiotemporal regulation of GLUT4 vesicle exocytosis is of great importance to explain the pathogenesis of diabetes and may provide new potential therapeutic targets." (PMID 28529958, 2017).
diabetes (continued). "Moreover insulin treatment from the onset of diabetes can ameliorate some but not all of these changes suggesting that glycaemic control, or at least the anabolic effects of insulin therapy, are important but are not sufficient to improve neutrophil function and wound healing." (PMID 28182694, 2017). "The modeling approach is intended for use in average insulin-treated diabetes populations in which the baseline HbA1c values are within an average range (6.5% to 11.5%); it is not intended for use in individuals or unique diabetes populations (eg, gestational diabetes)." (PMID 27510441, 2017). "Despite de fact that (a) relaxin shares its structure with insulin, (b) it seems to improve insulin resistance, and (c) its circulating levels are altered in diabetes, it is not clear whether or not relaxin could share with insulin the capacity to decrease blood glucose levels." (PMID 28868039, 2017). "Moreover, they suggested that due to the fact that NAD+ is also a cofactor for impairment of insulin sensitivity while insulin is crucial for podocyte function, diminished KMO activity in diabetes might contribute to the development of proteinuria in diabetic nephropathy." (PMID 28777303, 2017). "Moreover, increased intestinal inflammatory gene expression of TNF-α, IL-6, ICAM and PTGS-2 was found in insulin-resistant obese patients compared to non-insulin-resistant obese patients, suggesting that intestinal inflammation is involved in diabetes during obesity." (PMID 27620343, 2017). "Therefore, the effect of drinking on incident diabetes in Korean men may be explained by its impact on β-cell function, rather than insulin sensitivity." (PMID 28779170, 2017). "Due to known spikes in blood glucose levels in acutely ill patients with or without known diabetes, basal-bolus treatment regimen is recommended for non-critical ill patients’ hyperglycemia management, as it most closely mimics the body’s normal patterns of insulin secretion." (PMID 28970434, 2017). "However, in a study composed by men and women, circulating relaxin concentrations were lower in patients with T2DM than in controls but not related to component traits in patients with diabetes such as cholesterol, triglycerides, fasting blood glucose or fasting insulin." (PMID 28868039, 2017). "DKD is a chronic complication of both type 1 diabetes mellitus (DM) (beta cell damage, absolute lack of insulin) and type 2 DM (insulin resistance and/or decreased secretion of insulin).There are five stages in the development of diabetic nephropathy." (PMID 28197499, 2016). "In addition, post initiation of anti-tubercular treatment, TB drugs such as rifampicin and isoniazid may also induce hyperglycemia by enhancing the metabolism of hypoglycemic agents in anti-diabetes drugs, and impairing insulin secretion in non-diabetics." (PMID 27798659, 2016). "This is supported by previous findings that diabetes is strongly driven by insulin resistance in black (African) and Middle Eastern populations in contrast to South Asians, where diabetes is mostly driven by impaired insulin secretion rather than insulin resistance." (PMID 27938404, 2016). "However, our findings are in agreement with a previous study conducted on adult patients with T1DM which demonstrated that circulating OPN levels directly correlate with higher BMI, SBP, and DBP, and lower HDL, but not with diabetes complications, insulin dose, C-peptide level, or disease duration." (PMID 27353561, 2016). "Although the four top-ranked clinical traits (insulin treatment, baseline serum insulin levels, use of insulin-sensitising agents and baseline HbA1c levels) independently explained variance in diabetes remission, no obvious cutoff could be applied to separate remitters from nonremitters." (PMID 29263820, 2016).
diabetes (continued). "For people with impaired fasting glucose, who are known to have reduced insulin sensitivity and β cell dysfunction, a mild single predictor such as ABI may not considerably contribute to discriminating their diabetes risk since they are already at high risk of diabetes." (PMID 27923363, 2016). "Keyword analyses show that smoking, diabetes, cardiovascular diseases and mental illnesses, as well as medication that can treat such medical conditions, such as non-steroid anti-inflammatory agents, insulin and antidepressants constitute the main topics of research." (PMID 27729352, 2016). "The disparity in phosphorylation observed in diabetes suggests that conformational changes within the Cx43 CT, or its interaction with other binding partners, may block the ability of PKC-ε to efficiently phosphorylate Cx43 at S368 in the setting of the non-insulin-treated diabetic heart." (PMID 27034963, 2016). "In patients with a diabetes duration of <5 years, some patients with type 1 diabetes may be still producing insulin (the ‘honeymoon’ period) and not yet treated with insulin, although it is rare for patients with type 1 diabetes to be without insulin for prolonged periods." (PMID 27080317, 2016). "However, ketoacidosis was not reported in the patients with diabetes, so one may consider that the residual pancreatic tissue secretes some insulin." (PMID 26758964, 2016). "When all patients with diabetes are considered, the authors hypothesise that the performance of the UK guidelines will be even better because the vast majority of patients who are not treated with insulin will be correctly classified as having type 2 diabetes." (PMID 27080317, 2016). "It seems that over stimulation of insulin-secreting cells in response to chronic ED administration was followed by increased insulin resistance, that was confirmed by the significant increase in HOMA-IR- calculated in this study, and cell exhaustion which might result in diabetes mellitus later on." (PMID 26894845, 2016). "Despite the recent introduction of new types of insulin, insulin delivery systems, and innovative blood glucose (BG) monitoring technologies to improve T1D self-management and BG control, non-adherence to a diabetes management regimen remains common, especially in young adolescents with T1D." (PMID 27468762, 2016). "However, there are a certain number of patients with GADAb-positive diabetes who do not progress to insulin-requiring diabetes for many years, and their clinical and genetic characteristics remain unclear." (PMID 27177031, 2016). "However, we cannot rule out the possibility that diabetes might contribute to endothelial dysfunction considering that the subjects with obesity also had higher fasting blood glucose and insulin levels compared with those in non-obese controls." (PMID 27000941, 2016). "However, a recent retrospective analysis of a large pediatric cohort showed that only a small portion of MODY subjects were properly diagnosed in spite of having negative pancreatic autoantibodies, preserved endogenous insulin production, or strong family history of diabetes in multiple generations." (PMID 26942212, 2016). "The barriers to safe disposal of sharps by diabetes patients include lack of information about how and where to dispose, lack of proper advice from healthcare practitioners, wrong perception on sharp disposal, and self-administration of insulin by diabetic patients." (PMID 27738637, 2016). "Recent evidence has shown that when SMBG is performed in a structured manner, and is coupled with appropriate feedback and education, it may lead to positive health behavior change amongst patients with type 2 diabetes mellitus (T2DM) who are not treated with insulin." (PMID 27542325, 2016).
diabetes (continued). "In patients with diabetes or with high level of glucose, miR-30d could regulate Map4k4 expression to increase the levels of insulin transcription factors, thus promoting the insulin secretion and reducing TNF-α-induced transcription and production of insulin genes." (PMID 28066696, 2016). "However, the absence of direct measures of insulin resistance (eg, based on glucose clamp methods) could have led to an underestimation of the true relationship between copeptin and incident diabetes." (PMID 26158609, 2015). "However, during this trial, strict insulin titration protocols where used, which may not reflect real-life diabetes management." (PMID 26292721, 2015). "Diabetes mellitus (DM) is a complex and multisystem disease characterized by elevated blood glucose levels resulting from either a lack of insulin production or resistance to insulin." (PMID 25658748, 2015). "Moreover, diabetes suppressed the genes responsible from carbohydrate metabolism which could be explained by the inability of blood glucose usage in the absence of insulin." (PMID 25905778, 2015). "Very low plasma insulin levels in STZ-diabetic rats after a glucose overload have been observed, which could explain our data related to the impaired glucose tolerance in rats with 4 and 19 days of diabetes, related to experiments carried out for 1 and 15 days, respectively." (PMID 26064170, 2015). "Individuals with low SMI with and without diabetes demonstrated increased insulin resistance, hyperinsulinemia, and increased levels of glycosylated hemoglobin compared with individuals with higher SMI, which was probably caused by decreased insulin levels in the target organ." (PMID 26346157, 2015). "Additionally, while we did not exclude diabetic patients (no insulin dependent diabetic patients met inclusion criteria), one should consider not allowing patients with poorly controlled diabetes and/or peripheral neuropathy to bear weight immediately due to soft tissue healing concerns." (PMID 25785201, 2015). "A substantial lack of insulin effects manifests itself clinically as diabetes mellitus and studying and understanding the stimulus-secretion coupling in ever-increasing detail is crucial to understanding the pathophysiology of diabetes mellitus and to find new treatment modalities." (PMID 26516866, 2015). "However, it is not known whether these influence of diabetes is solely due to the disappearance of daily variations of PAI-1 in patients with diabetes or that changes in insulin levels and insulin resistance might also be important contributors." (PMID 26089884, 2015). "Ninety-two patients without diabetes with planned elective CS procedures at a tertiary institution were evaluated preoperatively and 3 months postoperatively for measures of glucose control including hemoglobin A1c, fasting plasma glucose, 2-h post oral glucose load, and insulin levels." (PMID 26322019, 2015). "Fourth, other relevant variables such as years since diabetes diagnosis, type of diabetes, insulin use or glycemic control are not collected by the surveys used and may act as confounding factors since some of them have been found to be associated with adherence." (PMID 26121575, 2015). "However, while hyperglycemia represents the essential disorder of untreated type 1 diabetes mellitus, modern research reveals that many adverse consequences of type 2 diabetes mellitus are not a function of hyperglycemia, but rather of lipid and insulin excess." (PMID 24949486, 2014). "Moreover, the application of TATA-box-targeting siRNAs to specifically activate some important genes, such as insulin, tumor repressor genes (p21) or DNA repair genes (BRCA2), may provide a new safe treatment strategy for many diseases such as cancer and diabetes." (PMID 25250958, 2014).